CDK5 (cyclin dependent kinase 5)
Diseases named in the same sentence as CDK5 in open-access papers (continued):
Sharing a sentence is not in itself a finding about the gene and the disease.
tumor (150 papers, 2010 to 2026). "High LIMK1 or CDK5 expression was significantly associated with pathological N stage and tumor grade (P < 0.05)." (PMID 40476449, 2025). "Apart from neurodegenerative disorders, amplification and increased expression of CDK5 have been described in multiple tumor types and are associated with worse prognosis and stemness." (PMID 36839989, 2023). "On the contrary, an increased cyclin-dependent kinase 5 (CDK5) regulatory subunit-associated protein 3 in HCC accelerated tumor metastasis bound to and activated PAK4." (PMID 36672500, 2023). "CDK5 expression level was significantly associated with age, tumor grade, histological type and vital status in both TCGA and GSE16011 cohorts." (PMID 34093802, 2021). "We found that CDK5 was associated with tumor metabolism and CDK5 knockdown inhibited cell proliferation and colony forming ability, and promoted apoptosis and cell cycle arrest." (PMID 34093802, 2021). "Conclusively, pharmacologically diminishing tumor cells stemness transformation by targeting the CDK5/pho‐PPARγ axis causes an obvious immunophenotyping shift, thus augmenting the efficacy of anti‐PD‐1 therapy in TNBC." (PMID 33240752, 2020). "Studies have assessed the association between Cdk5 and survival; however, this has been in tumour types other than breast." (PMID 32352232, 2020). "Cytoplasmic Cdk5 expression was associated with Figo stage, residual disease and histological subtype, with nuclear Cdk5 expression associated with tumour grade in addition." (PMID 32588513, 2020). "Low cytoplasmic Cdk5 expression was associated with lower Figo stage (χ2 = 13.172, df = 3, P = .004) tumour histology (χ2 = 33.852, df = 6, P < .001) and the absence of residual disease (χ2 = 14.121, df = 2, P = .001)." (PMID 32588513, 2020). "In the current study, we also demonstrated an association with ER status, with low nuclear Cdk5 expression associated with ER‐positive tumours." (PMID 32352232, 2020). "In this tumor model, loss of Cdk5 results in persistent expression of IRF2 and IRF2BP2, which likely leads to reduced PD-L1 expression on tumors thereby promoting anti-tumor immunity." (PMID 35582274, 2019). "Taken together, our results indicate that Nestin regulates the stability of lamin A/C by protecting it from Cdk5-dependent proteasomal degradation, and Nestin deficiency can drive tumor cell senescence." (PMID 30190500, 2018). "We also investigated possible association of nestin with tumor cells apoptosis by examining the expression of CDK5 and P35 using immunohistochemistry." (PMID 24966803, 2014). "Finally, high CDK5 expression was reported to correlate with a poor patient outcome: high CDK5 expression was associated with an advanced stage, poor differentiation, an increased tumor size, and poor patient prognosis." (PMID 37511490, 2023). "Finally, low expression of DARPP‐32 in tumours with high expression of Cdk5 or PP1 was more strongly associated with shorter survival that the alternative combinations." (PMID 32588513, 2020). "CDK5 has been implicated to play a role in various aspects of tumorigenesis and tumour progression." (PMID 31910742, 2020). "We also investigated the predictive value of Cdk5 through analysis of the association between tumor protein expression and the outcome of metastatic CRC patients receiving two standard chemotherapy regimens: Oxaliplatin plus 5-fluorouracil and irinotecan plus 5-fluorouracil." (PMID 31614664, 2019). "A decreased tumor number and size were found in Cdk5-deficient mice, which proved our hypothesis in vivo." (PMID 31272499, 2019). "Tumor volume in Dinaciclib-treated mice was significantly inhibited compared with placebo and untreated groups, indicating that loss of CDK5 could inhibit the tumorigenesis of NSCLC (P < 0.05)." (PMID 31496920, 2019). "Moreover, the contribution of endothelial Cdk5 to tumor angiogenesis and the underlying mechanism such as the Dll4/Notch driven angiogenic signaling are important subjects of this work." (PMID 26755662, 2016).
tumor (continued). "Given other documented anti-tumor roles of CDK5 in other immune cell subsets and tumor-associated immune checkpoint molecule expression, global targeting of CDK5/p35 in tumor-bearing hosts may represent a multi-pronged approach to novel immuno-oncology therapy." (PMID 41041338, 2025). "Low nuclear Cdk5 expression was associated with lower Figo stage (χ2 = 15.327, df = 3, P = .002), lower tumour grade (χ2 = 6.211, df = 2, P = .045), absence of residual disease (χ2 = 8.107, df = 2, P = .017) and tumour histology (χ2 = 26.522, df = 6, P < .001)." (PMID 32588513, 2020). "By controlling angiogenesis and immune surveillance, Cdk5 can impact the dynamics of the anti-tumor response, highlighting it as a significant, yet complex, therapeutic target." (PMID 41369365, 2025). "Mechanistically, nuclear Cdk5 acts as a tumor suppressor by inducing the expression of the Cdk family inhibitor p16INK4a, thereby inhibiting the cell cycle." (PMID 41369365, 2025). "CDK5 also acts as a crucial regulator of tumour angiogenesis by contributing to endothelial cell survival and migration." (PMID 39739588, 2025). "Upon delivery to the tumor cells, the released Cas9-Cdk5 knocks out the Cdk5 gene and reduces PD-L1 expression on tumor cells to restore cytotoxic T-cell activity." (PMID 40872479, 2025). "Consistent with this, a small molecule (NS-0011) that binds the NES region of Cdk5 promotes its nuclear accumulation and suppresses tumor growth, validating this transport machinery as a therapeutic target." (PMID 41369365, 2025). "Based on these findings, we proposed a combined therapeutic strategy of simultaneously targeting LIMK1 and CDK5 for the treatment of tumor metastasis, especially in ESCC." (PMID 40476449, 2025). "In parallel with cell-intrinsic programs, Cdk5 also remodels the tumor microenvironment—blood vessels and immunity—that feeds back on tumor behavior." (PMID 41369365, 2025). "The oncogenic potential of Cdk5 is thus multifaceted, contributing not only to these core metabolic programs but also to the emergence of tumor heterogeneity, as observed in pancreatic neuroendocrine tumors." (PMID 41369365, 2025). "Cyclin‐dependent kinase 5 (CDK5) is an unusual member of the family of cyclin‐dependent kinases, involved in tumour growth and angiogenesis." (PMID 39739588, 2025). "This tumor-suppressive function also extends to enhancing treatment efficacy, as nuclear Cdk5 has been shown to promote apoptosis and attenuate chemoresistance via the DP1–E2F1 axis." (PMID 41369365, 2025). "Cdk5 also actively shapes the tumor microenvironment by promoting angiogenesis and modulating immunity." (PMID 41369365, 2025). "Collectively, these data suggest that upregulation of LIMK1 and CDK5 activates β‐catenin, promoting tumor metastasis and correlating with poor prognosis in ESCC." (PMID 40476449, 2025). "In other word, inhibition of CDK5 can significantly up-regulate the expression level of PD-L1 in tumors and improve the efficacy of T-cell-mediated tumor immunotherapy." (PMID 39959665, 2025). "Inhibition of CDK5 with Roscovitine disrupts these immune checkpoint pathways, reducing PD-L1 levels and alleviating tumor-driven immune suppression." (PMID 41561738, 2025). "The activity of CDK5 is regulated by its activator p35, whose levels increase in aging and tumor cells." (PMID 40725041, 2025). "CDK5 directly influences the ubiquitination and degradation of PD-L1, thereby modulating anti-tumor immune responses." (PMID 39315102, 2024). "Studies have shown that combining CDK5 inhibitors with immune checkpoint inhibitors (ICIs) can significantly enhance the efficacy of immunotherapy, effectively inhibiting tumor initiation and progression." (PMID 39315102, 2024). "In vitro experiments revealed that the CRISPR-based gene expression platform exhibited superior CDK5 expression inhibition efficiency and specific cytotoxicity towards tumor cells." (PMID 38724931, 2024).
tumor (continued). "Overall, these results underscore that CDK5’s nuclear residence drives its function as a tumor suppressor." (PMID 37993880, 2023). "Accumulating evidence indicates that CDK5 is a master regulator of various oncogenic processes, including tumorigenesis, metastasis, angiogenesis, chemoresistance and tumor immunity." (PMID 37993880, 2023). "Nevertheless, a role for CDK5 in tumor immune evasion through the regulation of PD-L1 was suggested." (PMID 36839989, 2023). "CDK inhibitors hold immense promise in halting tumor development, progression, and metastasis, mediated through diverse pathways such as CDK5–FAK, PPARγ, PP2A, Hippo, and Wnt/β-catenin, among others." (PMID 37887415, 2023). "Reconstitution of CDK5 into tumor cells significantly increased apoptosis rates in both cell lines (all p < 0.05)." (PMID 37990321, 2023). "As expected, CDK5 depletion elicited a strong T-cell-mediated immune response by downregulating PD-L1, resulting in suppressed 4T1 tumor growth and inhibited lung metastasis." (PMID 37993880, 2023). "An in vivo tumor xenograft model of CDK5 overexpression combined with oxaliplatin treatment was established to verify the in vitro findings of the cytotoxicity assay." (PMID 37990321, 2023). "With the recognition of elevated succinate causing aberrant activation of CDK5, the anti-CDK5 inhibitor MRT3-007 was shown to suppress tumor growth in vitro as well as in xenograft mouse models with SDHB knockout." (PMID 36897220, 2023). "This unique function of CDK5 as a tumor suppressor has been attributed to its nuclear localization in these tissues." (PMID 37993880, 2023). "TP5, a small 24-amino-acid peptide developed at the National Institutes of Health (NIH), specifically inhibits the tumor-related CDK5/p25 activity while preserving the normal endogenous CDK5/p35 form and its physiological functions." (PMID 37511490, 2023). "Equally importantly, CDK5’s tumor-suppressive functions are mainly attributed to its nuclear localization in these tissues." (PMID 37993880, 2023). "Further, we revealed miR-152 to be a tumor-suppressive miRNA that reduces the expression of p35 and inhibits the activation of CDK5-p25 complex in the nucleus of ES cells." (PMID 37899376, 2023). "Based on the findings, it appears that cytoplasmic CDK5 is oncogenic, and nuclear CDK5 is tumor-suppressive." (PMID 37993880, 2023). "Upon TP5 treatment, CDK5 activity is inhibited, leading to a reduction in the DNA damage repair capacity of the tumor cells." (PMID 37511490, 2023). "Cyclin-dependent kinase 5 (Cdk5) is a cyclin-dependent neuronal-specific kinase, which is of great significance in tumor and neurodegenerative disorders." (PMID 37901140, 2023). "The expression of PD-L1 on tumor cells was significantly attenuated by knocking out Cdk5, leading to effective tumor growth inhibition in murine melanoma and lung metastasis suppression in triple-negative breast cancer." (PMID 36139078, 2022). "Proteogenomic integration analysis indicated that SND1 and CDK5 amplifications on chromosome 7q were associated with the activation of STAT3, which was relevant to tumor proliferation." (PMID 35659036, 2022). "In an animal study using the CRISPR-Cas9 genome editing system, PD-L1 was attenuated by specifically knocking out CDK5 to enhance host anti-tumor immunity." (PMID 35309935, 2022). "In contrast, p25-expressing neoplastic mice were able to survive the experiment and it was shown that CDK5 levels in the tumor cells of these mice were significantly lower." (PMID 33805800, 2021). "While Cdk5 plays a role in promoting tumorigenesis, there is also evidence supporting its anti-tumor effects." (PMID 34814918, 2021). "These PTMs are found to be essential for modulating the activity of CDK5 during tumor occurrence and development." (PMID 35006426, 2021).
tumor (continued). "To determine if high expression of LMW-E and CDK5 are associated with RFS, we performed the univariable analysis with LMW-E and CDK5 as well as standard markers of clinical outcome such as tumor grade and TNM staging." (PMID 33990543, 2021). "Studies have shown that CDK5 modulated the ERK5 AP‐1 signaling axis to promote tumor multiplication, formation, and invasion of CRC." (PMID 33620152, 2021). "The inhibition of CDK5 kinase activity was linked to suppression of DDR process and tumor progression." (PMID 35006426, 2021). "Instead, comparable levels between tumours and normal mammary glands were found for Cdk3, Cdk5, and Cdk6." (PMID 34646365, 2021). "In the case of medulloblastoma, disturbances in the expression of CDK5 allow the development of this tumor by deceiving the T lymphocytes, in order to evade detection by the immune system." (PMID 33805800, 2021). "In this study, analyses results from TCGA and GSE16011 datasets showed that high CDK5 expression level was correlated with poor prognosis and advanced clinicopathological parameters such as age, tumor grade and histological type." (PMID 34093802, 2021). "It was shown that the proportion of U251MG cells in the G1 and G2/M phases was significantly higher and that in the S phase was significantly lower in the sh-CDK5 group than in the sh-NC group, indicating that CDK5 knockdown inhibited tumor proliferation." (PMID 34093802, 2021). "In glioblastoma, Cdk5 phosphorylates a ubiquitin E3 ligase TRIM59 at Ser 308, which subsequently induces the degradation of macroH2A1, a tumor suppressive histone variant." (PMID 34814918, 2021). "The details for how the sumoylation of CDK5 is involved in regulating the occurrence and development of tumor remain to be studied." (PMID 35006426, 2021). "Cdk5 phosphorylates and activates the tumor suppressor DLC1, thus reducing the size of xenografted tumor in mice." (PMID 34814918, 2021). "Tumor biomarkers, such as cyclin-dependent kinase 5, neuron-specific enolase, and delta-like protein 3, were reported to be prognostic factors in previous studies." (PMID 34461929, 2021). "Recent studies have reported that CDK5 is dysregulated in various tumor cells, and it participates in tumorigenesis." (PMID 34093802, 2021). "The data reviewed above provide robust evidences to propose the inclusion of CDK5 and its PTMs in the group of novel molecules to be tested in preclinical research aiming at tumor intervention." (PMID 35006426, 2021). "In GBM tumorigenicity, Tyr15 phosphorylation of CDK5 activated by EGFR phosphorylates TRIM59 at Ser308 to promote tumor growth." (PMID 35006426, 2021). "Animal studies also demonstrated that knockdown of Cdk5 inhibited tumor growth, while levels of cyclin D1 and c-Myc expression were markedly decreased in the Cdk5 knockdown group vs. control group." (PMID 33488528, 2020). "CR8 was shown to target similar Cdks as Roscovitine including Cdk1, Cdk2, Cdk5, Cdk7 and Cdk9, but with much stronger efficacy and a predicted improved anti-tumor potential." (PMID 32380742, 2020). "CDK5 blockade not only results in profound metastasis abrogation but also promote anti‐tumor immunity." (PMID 33240752, 2020). "Nuclear and cytoplasmic expression of DARPP‐32, PP1 and Cdk5 was observed and staining varied from weak to intense, with heterogeneity observed between adjacent tumour cells." (PMID 32588513, 2020). "CDK5RAP3 itself encodes CDK5 regulatory subunit associated protein C53 (Cdk5rap3, also known as C53 and LZAP) that is a probable tumor suppressor involved in signaling pathways governing transcriptional regulation and cell cycle progression." (PMID 32983988, 2020). "Ki67 (a proliferation marker) decreased and apoptosis was induced in the tumor tissues after CDK5 inhibition, and the combination exerted additive effects." (PMID 33240752, 2020).
tumor (continued). "According to this model, depletion of CDK5 increases the levels of nuclear Foxo1, which leads to increased expression of Bim protein and tumour cell apoptosis." (PMID 31910742, 2020). "Pharmacological interruption of CDK5 reverses immunosuppressive tumor microenvironment, and enhances anti‐PD‐1 curative effects." (PMID 33240752, 2020). "Different molecular mechanisms were postulated to mediate the function of CDK5 in tumour cell survival." (PMID 31910742, 2020). "According to this model, glucose deprivation or inhibition of CDK5 results in dephosphorylation of Noxa and translocation of Noxa to mitochondria leading to tumour cell apoptosis." (PMID 31910742, 2020). "Blocking CDK5/pho‐PPARγ significantly reduces CD44v+ BCSCs population in tumor tissues, thus abrogating metastatic progression in TNBC mouse model." (PMID 33240752, 2020). "Pearson's correlation analysis showed a significantly positive correlation between pho‐PPARγ and CDK5 in the tumor tissues (Pearson r = 0.5195, p < 0.001)." (PMID 33240752, 2020). "The pharmacological inhibition or genetic interruption of CDK5/pho‐PPARγ truly diminished tumor development in the TNBC mouse model." (PMID 33240752, 2020). "The addition of CDK5 inhibitor Dinaciclib significantly suppressed the tumorigenesis ability of NSCLC cells in tumor-bearing mouse model." (PMID 31496920, 2019). "It was also reported that cyclin-dependent kinase 5 (CDK5) was involved in the regulation of the Notch pathway in tumor angiogenesis." (PMID 31093499, 2019). "In this study, we found that the expression of CDK5 was significantly increased in HCC and that enhanced CDK5 expression was directly correlated with decreased survival, higher tumor recurrence, and vascular invasion." (PMID 31272499, 2019). "For instance, in pancreatic cancer, two studies showed that Cdk5 inhibition affected tumor malignant progression in vitro and in vivo." (PMID 31614664, 2019). "This study demonstrates that CDK5 promotes GBM tumor growth through TRIM59-mediated STAT3 signaling activation." (PMID 31488827, 2019). "Here, we showed that the high expression of CDK5 neutralized the tumor suppressing effect of BIN1 by phosphorylating c-MYC at Ser-62 site." (PMID 31496920, 2019). "Based on our observation that higher CDK5 expression was found in HCC tumor tissues, we postulated that CDK5 promotes HCC cell growth." (PMID 31272499, 2019). "By contrast, in high invasive 7721 cell lines, xenografting using sh-Cdk5–7721 cells resulted in smaller tumor formation and less liver metastasis compared with sh-control-7721 cells in immunocompromised mice." (PMID 31272499, 2019). "The CNV of the Cdk5 gene was strongly correlated (r = 0.55, p = 7.16 × 10−7) to Cdk5 expression levels in tumor tissue and also in a panel of 63 CRC cell lines (r = 0.54, p = 4.6 × 10−6) (Broad Institute Cancer Cell Line Encyclopedia)." (PMID 31614664, 2019). "Although the correlation of CDK5 and tumor has been reported for years, this study is the first to comprehensively show active CDK5 and its signaling pathway in tumorigenesis, development, and clinical outcomes of HCC." (PMID 31272499, 2019). "It is worth mentioning that our study was performed in a large number of CRC patients’ samples using different techniques to measure Cdk5 levels, and importantly, in selected groups according to tumor stage and clinical approaches." (PMID 31614664, 2019). "To identify the mechanism underlying the effect of active CDK5 promoting HCC development, we performed stable isotope labeling by amino acids in cell culture (SILAC) to screen substrates of CDK5 in tumor cells." (PMID 31272499, 2019). "Tumor cell growth was also significantly decreased as observed using Ki67 staining in DEN-induced Cdk5+/− mice compared with WT mice." (PMID 31272499, 2019).